AGTR1 (angiotensin II receptor type 1)
Diseases named in the same sentence as AGTR1 in open-access papers (continued):
Sharing a sentence is not in itself a finding about the gene and the disease.
congestive heart failure (18 papers, 2012 to 2025). Failure of the heart to pump a sufficient amount of blood to meet the needs of the body tissues, resulting in tissue congestion and edema. "Studies have found that the XinLi Formula alleviates chronic heart failure by regulating the interaction between AGTR1 and AQP1." (PMID 41333015, 2025).
Marfan syndrome (18 papers, 2007 to 2025). A disorder of the connective tissue. "Currently, the most promising therapeutic drug in Marfan syndrome is losartan, by blocking the angiotensin II receptor type 1 and thereby inhibiting pSmad2 signaling." (PMID 25238161, 2014). "Antagonists of the angiotensin II receptor type 1 (AT1), including the anti-hypertensive drug losartan, have been shown to block also the profibrotic action of transforming growth factor (TGF)-β and thereby ameliorate disease progression in mouse models of Marfan syndrome." (PMID 22943509, 2012).
Parkinson disease (18 papers, 2007 to 2025). A progressive degenerative disorder of the central nervous system characterized by loss of dopamine producing neurons in the substantia nigra and the presence of Lewy bodies in the substantia nigra and locus coeruleus. "DA neurons of the human adult substantia nigra pars compacta (SNc), corresponding to the ventral A9 region, are marked by the expression of SOX6 and AGTR1, express higher levels of PD-causative genes and have been shown to be more vulnerable to Parkinson’s disease (PD)." (PMID 41279649, 2025). "We have found that none of the analysed polymorphisms in the genes of renin-angiotensin system, i.e. rs699, rs4762 in AGT, rs5186 in AGTR1, rs5194, rs1403543 in AGTR2 or ACE I/D was associated with MCI or dementia in Parkinson’s disease." (PMID 34302265, 2021).
Sepsis (18 papers, 2013 to 2025). Sepsis is defined as life-threatening organ dysfunction caused by a dysregulated host response to infection. "Our study aims to define whether the AGTR1 polymorphism contributes to the course and outcomes of sepsis in patients admitted to the city hospital ICU facility." (PMID 34781995, 2021). "So, the aim of our study was to define the contribution of AGTR1 rs275651 genotypes to the course and outcomes of critical illness, complicated with sepsis." (PMID 34781995, 2021).
colorectal cancer (17 papers, 2010 to 2026). A primary or metastatic malignant neoplasm that affects the colon or rectum. "It was also shown that high expression of the AGTR1 gene encoding the AT1R protein correlated with poorer long-term colorectal cancer outcomes." (PMID 35879682, 2022). "High expression of AGTR1 will stimulate the expression of vascular endothelial growth factor (VEGF), the key growth factor controlling angiogenesis, and is associated with a poor prognosis for colorectal cancer." (PMID 36293321, 2022). "On the other hand, AGTR1 methylation was significantly found in non-small cell lung cancer (NSCLC) and colorectal cancer." (PMID 36344942, 2022). "They showed that AGTR1 methylation was found in 60% of NSCLC and 65% of colorectal cancers." (PMID 36344942, 2022).
glomerulosclerosis (17 papers, 2010 to 2025). A hardening of the kidney glomerulus caused by scarring of the blood vessels. "Aberrant activation of AGTR1 in DKD is a major driver of proteinuria and glomerulosclerosis." (PMID 40995593, 2025).
fibrosis (16 papers, 2013 to 2024). the formation of excess fibrous connective tissue in an organ or tissue in a reparative or reactive process. "Earlier studies, set out to examine AT1R in rat, mice, or human liver, were designed to determine AGTR1 expression and AT1R protein synthesis depending on the stage of liver disorder such as fibrosis, cirrhosis, cholestasis, or NAFDL." (PMID 35229169, 2022).
lung cancer (16 papers, 2016 to 2024). A malignant neoplasm involving the lung. "In lung cancer, AGTR1 inhibits the progression of lung adenocarcinoma by promoting the PI3K/AKT3 pathway." (PMID 36983741, 2023). "For example, a large-scale study of estrogen receptor-positive breast cancer tumors revealed an increase in AGTR1 mRNA expression, which is the opposite of what we observed in the lung cancer study from which this data is derived." (PMID 28791183, 2017). "AGTR1 is primarily involved in the renin-angiotensin system and has previously been validated as an important tumor suppressor in lung cancer, cholangiocarcinoma, colon cancer and liver cancer." (PMID 28178311, 2017). "Given the potential toxicity of targeting nAChR or Src46,47, the inhibition of the RA system by ACE inhibitors or AGTR1 antagonists that are prescribed to hypertensive patients without major complications would be an effective strategy for the prevention of lung cancer in smokers." (PMID 37258578, 2023). "By intersecting these top DEGs, we recognized seven genes potentially involved in the pathogenesis of both SSc and lung cancer: SCN7A, AGTR1, WIF1, PRKG2, LTF, AQP4, and COL10A1." (PMID 39744538, 2024). "In a panel of 28 cell lines tested for AGTR1 expression, the two cell lines with the highest AGTR1 mRNA expression were of NEN origin, whereas only one colon and one lung cancer cell line reached similarly high values." (PMID 33120925, 2020).
viral infection (16 papers, 2004 to 2025). "Expression of ACE2, TMPRSS2, and AGTR1 was analyzed, and the impact of viral infection on ACE2 expression, vascular inflammation, and vascular morphology was assessed." (PMID 38576426, 2024). "While other renin-angiotensin system mediators, such as AGTR1, play a role in the resultant hypercytokinemia, ACE2 expression on the surface of EC is critical to the initial infection, and without adequate expression, viral infection fails to occur." (PMID 38576426, 2024).
acute respiratory distress syndrome (15 papers, 2020 to 2025). Progressive and life-threatening pulmonary distress in the absence of an underlying pulmonary condition, usually following major trauma or surgery. "Here the imbalance of AGTR1:2 signalling compounded by the downregulated effects of ACE2, via Angiotensin 1–7 controlled Mas receptor signalling, may be key in the development of an unopposed pro-inflammatory state seen in the pandemic and possibly acute respiratory distress syndrome (ARDS)." (PMID 34051791, 2021).
gastric cancer (15 papers, 2010 to 2024). A primary or metastatic malignant neoplasm involving the stomach. "BLACAT2 is upregulated in bladder cancer 45, gastric cancer 46, and colon cancer 47 and negatively mediates the expression of AGTR1 and MAS1." (PMID 34671200, 2021). "Further study found that AGTR1 was closely related to tumor immune infiltration and invasion and may be a new therapeutic target gene for gastric cancer." (PMID 36983741, 2023). "A novel liquid biopsy method using a 4‐mRNA biomarker panel (AGTR1, DNER, EPHA7, SUSD5) improves early detection of recurrence in locally advanced gastric cancer." (PMID 39556695, 2024). "The study identified a panel of four mRNAs (AGTR1, DNER, EPHA7, and SUSD5) significantly upregulated in recurrent gastric cancer tissues compared to non‐recurrent tissues." (PMID 39556695, 2024). "We reviewed a lot of literature and found that AGTR1, as one of the important coding genes of the RAS system, played an important role in various tumors, but in gastric cancer, there was a lack of in-depth research." (PMID 36983741, 2023).
Hypercholesterolemia (15 papers, 2008 to 2023). An increased concentration of cholesterol in the blood. "The predicted indication for AGTR1 is hypercholesterolemia, also known as high cholesterol." (PMID 30736745, 2019).
pulmonary arterial hypertension (15 papers, 2014 to 2024). Pulmonary arterial hypertension (PAH) is a group of diseases characterized by mean pulmonary artery pressure >20 mmHg and elevated pulmonary arterial resistance leading to right heart failure. "Similarly, H19 may promote the pathogenesis of pulmonary arterial hypertension (PAH) by targeting let-7b to enhance angiotensin II receptor type 1 (AT1R) expression and smooth muscular cell proliferation." (PMID 32272875, 2020).
glioma (14 papers, 2001 to 2025). A benign or malignant brain and spinal cord tumor that arises from glial cells (astrocytes, oligodendrocytes, ependymal cells). "The present study examined the association between AGTR1 expression and survival time in glioma patients and evaluated the anti-GBM effect of three ARBs that can penetrate the blood–brain barrier." (PMID 37291545, 2023). "Losartan, an FDA-approved AGTR1 inhibitor, has been particularly explored in recent studies where it was shown to reduce glioma cell line growth in vitro as well as in vivo in a U87 xenograft model." (PMID 38607073, 2024). "To assess the relationship between AGTR1 and glioma-related genes and other factors, we performed multivariate analysis of factors related to overall survival with data for 688 glioma cases from the TCGA dataset." (PMID 37291545, 2023). "The results revealed that older age (≥ 52 years old), high-grade glioma, and high expression of AGTR1, NF1, and AxL were independent prognostic factors." (PMID 37291545, 2023). "RT‒PCR analysis revealed that the mRNA expression level of AGTR1 was significantly higher in glioma cell lines than in normal brain tissue." (PMID 37291545, 2023). "One view is the same as mainstream studies, that LINC00665 is upregulated as an oncogenic factor and promotes glioma progression through a ceRNA mechanism (LINC00665/miR-34a-5p/AGTR1)." (PMID 35563845, 2022). "recently reported that LINC00665 sponges miR-34a, which targets the angiotensin II receptor type I (AGTR1) gene to impede glioma malignancy." (PMID 35223453, 2021). "AGTR1 was considered an indicator of a poor prognosis in GBM patients even after multivariate analysis to eliminate potential confounding effects with other glioma-related genes." (PMID 37291545, 2023). "We next analyzed AGTR1 mRNA levels in various glioma cell lines." (PMID 37291545, 2023). "In addition, we performed in silico analysis of AGTR1 expression in human glioma samples of various histological grades from the GENT2 database." (PMID 37291545, 2023). "AGTR1 was significantly overexpressed in WHO grade IV GBM compared with WHO grade I, II, and III gliomas." (PMID 37291545, 2023). "In glioma, LINC00665 can sponge miR-34a-3p, thereby upregulating AGTR1, promoting tumor growth and invasion." (PMID 35563845, 2022). "ACEI and AGTR1 inhibitors could prolong the OS and PFS of glioma patients." (PMID 34671200, 2021).
hepatocellular carcinoma (14 papers, 2011 to 2026). A malignant tumor that arises from hepatocytes. "The data mining analysis showed that AGTR1 expression was significantly increased in human hepatoma HepG2 cells treated with the demethylation agent 5-aza-2’-deoxycytidine (fold = 3.12, p = 0.009)." (PMID 31538912, 2020). "Thus, we demonstrate cyclosporine treatment of human hepatoma cells to significantly reduce DNA-binding of HNF4α to AGT and AGTR1 at gene specific promoters to cause impaired gene expression." (PMID 21298017, 2011). "Up-regulation of AGTR1 expression by nuclease domain containing-1 promotes cell invasion and migration, which in return activates the ERK signaling pathway in hepatocellular carcinoma." (PMID 28073349, 2017).
melanoma (14 papers, 2010 to 2025). A malignant, usually aggressive tumor composed of atypical, neoplastic melanocytes. "In addition, ectopic expression of the AGTR1 gene in melanoma cell lines led to cell death, while the loss of AT1R was suggested to be associated with a melanoma-aggressive phenotype." (PMID 34539580, 2021). "This is supported by heightened CpG island methylation of AGTR1 and its reduced expression in metastatic melanoma compared to primary melanoma." (PMID 39941158, 2025). "Although AT1R is known as an oncogenic receptor with a proliferative effect, a recent study showed the AGTR1 (encoding AT1R) suppressor effect following ectopic expression of AGTR1 (encoding AT1R) in melanoma cell lines lacking endogenous expression of AT1R." (PMID 37396936, 2023). "Furthermore, antagonizing AT1R with an ARB or shRNA-mediated knockdown in melanoma cells lines expressing AGTR1, allows the cell lines to proliferate in serum-free conditions." (PMID 35574555, 2022). "It has been suggested that AGTR1 methylation is a late event in melanoma development." (PMID 34639015, 2021). "However, blockade of angiotensin II receptor type 1 results in increased cell growth, suggesting different roles for the different angiotensin receptors in melanoma, which could explain the increased mitotic rate seen in case 5 with oral malignant melanoma." (PMID 38922022, 2024). "In an AGTR1 gene-lacking melanoma mice model, Ang II treatment did not affect cell proliferation, and the pulmonary metastasis was suppressed." (PMID 34539580, 2021). "With regards to AT2R, Ang II treatment promotes cell proliferation in AGTR1 gene-lacking melanoma cells but not in AGTR1 and AGTR2 genes lacking melanoma cells, which proves the Ang II-dependent proliferative effect of AT2R." (PMID 34539580, 2021).
systemic sclerosis (14 papers, 2014 to 2024). A chronic disorder, possibly autoimmune, marked by excessive production of collagen which results in hardening and thickening of body tissues. "Agonistic autoantibodies (Aabs) against the angiotensin II receptor type 1 (AT1R) and the endothelin receptor type A (ETAR) have been identified in patients with systemic sclerosis (SSc)." (PMID 24612997, 2014). "Systemic sclerosis IgGs contain a multitude of SSc disease-specific and non-specific antibodies, including agonistic autoantibodies against angiotensin II receptor type 1 and the endothelin receptor type A." (PMID 28228756, 2017).
dementia (13 papers, 2013 to 2025). Loss of intellectual abilities interfering with an individual's social and occupational functions. "Similarly, the CC genotype of AGTR1 rs5186 was associated with dementia only at baseline." (PMID 33802165, 2021). "The gene expression of mediators of cRAS signaling, ACE1 and AGTR1, and AGTR2, calibrated to RGs, was unaltered in all 3 dementia subtypes." (PMID 37813091, 2024).
Hepatic steatosis (11 papers, 2013 to 2025). Steatosis is a term used to denote lipid accumulation within hepatocytes. "The deletion of angiotensin II type 1 receptor in animal studies has been shown to reduce hepatic steatosis suggesting AGTR1 is an important regulator of hepatic steatosis." (PMID 23484035, 2013).
ischemic stroke (11 papers, 2011 to 2023). A stroke disorder caused by obstruction of blood flow to the brain, due to thrombotic (local blood clot formation) or embolic (due to a blood clot or other material traveling from another site) event. "The polymorphisms associated with an increased risk of ischemic stroke were the AGT M235T (p = 0.003), the AGT T174M (p = 0.001), and the AGTR1 A1166C (p = 0.001)." (PMID 38025202, 2023). "The aim of this study was to examine the association between AGTR1 A1166C and TSP-1 N700S polymorphisms and ischemic stroke in a young Mexican population." (PMID 38025202, 2023). "We identified that AGTR1 A1166C, AGT M235T, and AGT T174M polymorphisms were associated with an increased risk of ischemic stroke in Mexican young individuals." (PMID 38025202, 2023).
diabetic retinopathy (10 papers, 2011 to 2024). "Genetic variations in genes such as angiotensinogen (AGT), angiotensin-converting enzyme (ACE), and angiotensin II receptor type 1 (AGTR1) have been associated with an increased risk of diabetic retinopathy." (PMID 38918766, 2024).
pneumonia (10 papers, 2020 to 2024). An acute, acute and chronic, or chronic inflammation focally or diffusely affecting the lung parenchyma, caused by an infection in one or both of the lungs (by bacteria, viruses, fungi, or mycoplasma.). "In the lungs, over-activation of angiotensin II receptor type 1 (Ang2-AT1R) leads to severe lung injury and lung failure due to pneumonia." (PMID 33935717, 2021).
left ventricular hypertrophy (9 papers, 2010 to 2022). Enlargement of the LEFT VENTRICLE of the heart. "However, polymorphisms in AGTR1, and particularly the A1166C polymorphism (rs5186), have been associated with inflammation and left ventricular hypertrophy." (PMID 20308035, 2010). "Both ALOX15 and AGTR1 are likely to play important roles in inflammation, one of the primary putative mechanisms for the impact of air pollution on CVD and also an important mechanism involved in the development of left ventricular hypertrophy." (PMID 20308035, 2010).
cardiomyopathy (8 papers, 2010 to 2024). A disease of the heart muscle or myocardium proper. "In this meta-analysis, we reviewed all eligible studies that evaluate the associations between ACE I/D, AGT M235T, and AGTR1 A1166C gene polymorphisms and the risk of cardiomyopathy." (PMID 38166133, 2024). "In studies validated with Hardy-Weinberg principle, there was an association between AGTR1 polymorphism and cardiomyopathy risk under the dominant model with a pooled OR of 4.289 (AA+CA vs CC: 95% CI = 0.219–83.934; P = 0.001)." (PMID 38166133, 2024). "There is an association between AGTR1 gene polymorphisms and risk of cardiomyopathy under the specific model." (PMID 38166133, 2024). "These limitations highlight the need for further research to explore the potential impact of different ethnicities and gene-environment interactions on the association between ACE D/I, AGTR1 A1166C, and M235T polymorphisms with cardiomyopathy." (PMID 38166133, 2024). "In studies validated without Hardy-Weinberg principle, there was an association between AGTR1 polymorphism and risk of cardiomyopathy with pooled ORs of 0.595 (allelic model, A vs C: 95% CI = 0.451–0.785; P = 0.008) and 0.492 (dominant model, AA+CA vs CC: 95% CI = 0.369–0.1655; P = 0.001)." (PMID 38166133, 2024). "In this study, we conducted a systematic review and meta-analysis to summarize the findings regarding the impact of angiotensin converting enzyme (ACE) I/D, angiotensinogen (AGT) M235T, and angiotensin II Type 1 receptor (AGTR1) A1166C gene polymorphisms in patients with cardiomyopathy." (PMID 38166133, 2024). "Our comprehensive analysis, encompassing all available data, did not reveal a significant correlation between the AGTR1 A1166C polymorphism and cardiomyopathy." (PMID 38166133, 2024). "The ACE I/D gene polymorphisms were found to be associated with cardiomyopathy, while M235T and AGTR1 A1166C gene polymorphisms and cardiomyopathy were not significantly correlated." (PMID 38166133, 2024). "In the field of cardiomyopathies, the use of novel tracers targeted to specific pathways and receptors, such as myocardial angiotensin II receptor type 1, could shed further light on potential cardiomyopathic mechanisms." (PMID 37233187, 2023). "Similarly, linkages between AGTR1 A1166C and cardiomyopathy has been reported." (PMID 38166133, 2024).
glaucoma (8 papers, 2015 to 2021). Increased pressure in the eyeball due to obstruction of the outflow of aqueous humor. "Expressions of TLR4 and angiotensin II type 1 receptor (AGTR1) are increased in a mouse model of glaucoma, and an AGTR1 antagonist suppresses neurodegeneration in the mouse retina by inhibiting the TLR4-apoptosis signal-regulating kinase 1 pathway." (PMID 28053689, 2016).
Arrhythmia (7 papers, 2012 to 2024). Any cardiac rhythm other than the normal sinus rhythm. "Based on the functional analyses, other phenotypes (blood pressure and cardiac arrhythmia for AGTR1) and biological pathways (keratinization and cornified envelope for KRT28) related to CKD were also identified." (PMID 37210443, 2023).